STAR (steroidogenic acute regulatory protein)
Description:
Plays a key role in steroid hormone synthesis by enhancing the metabolism of cholesterol into pregnenolone. Mediates the transfer of cholesterol from the outer mitochondrial membrane to the inner mitochondrial membrane where it is cleaved to pregnenolone.
Synonyms: StARD1
Tractability: Small molecule: a structure with a bound ligand is known; it has a high-quality binding pocket.
Safety:
Unwanted effects reported when the protein is acted on. In parentheses: how it was acted on, where the effect was seen, and who reports it.
impaired, Fertility (inhibition; source: AOP-Wiki)
Malformation, Male reproductive tract (inhibition; source: AOP-Wiki)
Gene: Protein-coding gene on chromosome 8 (38,141,747 to 38,151,061, reverse strand). Ensembl gene ENSG00000147465.
Subcellular location: Mitochondrion outer membrane; Mitochondrion matrix
Pathways (Reactome):
Metabolism: Pregnenolone biosynthesis
Metabolism of proteins: Mitochondrial protein degradation
Gene Ontology:
Molecular function: cholesterol binding; cholesterol transfer activity; protein binding; molecular carrier activity; lipid binding
Biological process: glucocorticoid biosynthetic process; intracellular cholesterol transport; positive regulation of bile acid biosynthetic process; C21-steroid hormone biosynthetic process; regulation of steroid biosynthetic process; steroid biosynthetic process; cholesterol metabolic process; hormone biosynthetic process; steroid hormone biosynthetic process; sterol transport
Cellular component: mitochondrial matrix; mitochondrial outer membrane; mitochondrion; mitochondrial intermembrane space
Genetic constraint (gnomAD): Loss-of-function variants: 32 observed, 33.13 expected, observed/expected ratio (o/e) 0.97, 90% interval 0.73 to 1.3. The upper end of that interval is the gene's LOEUF score, 1.3, which puts it in group 5 of 6, group 1 being the genes least tolerant of losing a copy. Missense variants: 375 observed, 386.65 expected, observed/expected ratio (o/e) 0.97, 90% interval 0.89 to 1.06. Synonymous variants: 134 observed, 142.62 expected, observed/expected ratio (o/e) 0.94, 90% interval 0.82 to 1.08.
Homologues: Orthologues: chimpanzee STAR (99% identical), macaque STAR (97% identical), pig STAR (90% identical), rabbit STAR (89% identical), guinea pig STAR (89% identical), rat Star (88% identical), mouse Star (87% identical), dog STAR (84% identical), tropical clawed frog star (69% identical), zebrafish star (63% identical), Drosophila melanogaster Start1 (24% identical), Caenorhabditis elegans tag-340 (20% identical), and 1 more. Paralogues in human: STARD3 (35% identical), STARD5 (17% identical), STARD6 (15% identical), STARD4 (14% identical), STARD3NL (9% identical).
Diseases named in the same sentence as STAR in open-access papers:
STAR is named in the same sentence as 128 diseases in open-access papers, as found by Europe PMC text mining. Sharing a sentence is not in itself a finding about the gene and the disease. The quoted sentences say what the papers report.
congenital adrenal hyperplasia (51 papers, 2010 to 2026). Congenital adrenal hyperplasia (CAH) is an inherited endocrine disorder caused by a steroidogenic enzyme deficiency that is characterized by adrenal insufficiency and variable degrees of hyper or hypo androgyny manifestations, depending of the type and the severity of the disease. "Lipoid adrenal hyperplasia (LAH) is a rare severe form of congenital adrenal hyperplasia, which is caused by mutations in the STAR gene (8p11.2), encoding the transport protein StAR." (PMID 41640169, 2026). "Rare forms of CAH are caused by variants in CYP17A1 leading to delayed puberty, in STAR causing lipoid CAH, and in HSD3B2 with normal sexual differentiation and/or partial virilisation in females." (PMID 39253719, 2024). "A genetic study with targeted gene sequencing was done, which gave a final diagnosis of lipoid CAH (LCAH) due to a homozygous mutation of the steroidogenic acute regulatory protein (StAR) gene with autosomal recessive inheritance." (PMID 39229408, 2024). "Two homozygous mutations in StAR were found in intron 1 (c.64 + 1G > T), corresponding to lipoid adrenal hyperplasia." (PMID 39246559, 2024). "Mutations in the StAR locus result in congenital lipoid adrenal hyperplasia, in which steroid hormone biosynthesis is severely compromised." (PMID 35518925, 2022). "STAR plays a key role in aldosterone synthesis as mutations in STAR lead to deficiency in adrenal and gonadal aldosterone synthesis and are associated with lipoid congenital adrenal hyperplasia." (PMID 35197862, 2022). "On the other hand, Lipoid Congenital Adrenal Hyperplasia due to StAR defects, and P450scc and P450c17 deficiencies cause DSD in 46,XY newborns." (PMID 34987475, 2021). "Lipoid Congenital Adrenal Hyperplasia due to StAR defects, and cytochrome P450scc and P450c17 deficiencies cause DSD in 46,XY newborns." (PMID 34987475, 2021). "The severe classic lipoid CAH is life-threatening soon after birth due to (almost) complete loss of StAR activity causing severe glucocorticoid and mineralocorticoid deficiency." (PMID 32867102, 2020). "Various inactivating mutations in STAR result in lipoid congenital adrenal hyperplasia, a severe (and usually fatal) condition that manifests within the first weeks to months of life." (PMID 33243158, 2020). "We report a novel mutation within the StAR gene, causing congenital adrenal hyperplasia, with the so far unreported association with heterochromia iridis." (PMID 31666050, 2019). "STAR mutations resulting in lipoid congenital adrenal hyperplasia should be considered all over the world in the differential diagnosis of newborn babies and infants with primary adrenal insufficiency." (PMID 28637490, 2017). "Disruption of the STAR gene has been proven to cause congenital lipoid adrenal hyperplasia (CLAH), an endocrine disorder, causing mineralocorticoid deficiency which impairs the synthesis of all categories of adrenal steroids." (PMID 29232835, 2017). "The finding that STAR mutations are the genetic basis for lipoid CAH was key to establishing the essential role for StAR in ACTH-stimulated steroidogenesis as well as gonadotropin-stimulated steroidogenesis." (PMID 27999527, 2016). "So, any mutation in StAR protein, especially in cholesterol binding sites, causes hormonal abnormalities such as Lipoid Congenital Adrenal Hyperplasia, PCOS, and endometriosis." (PMID 27141537, 2015). "Mutations in the StAR gene were first described in patients with classic congenital lipoid adrenal hyperplasia (CLAH) in which both the adrenals and the gonads seemed to completely lack steroidogenesis." (PMID 21647419, 2011). "This conclusion is most powerfully established by the observation that StAR is the factor that is mutated in lipoid congenital adrenal hyperplasia, illustrating how scientific theories and models are most convincing when wholly independent approaches lead to the same conclusion." (PMID 39773408, 2025).
congenital adrenal hyperplasia (continued). "Congenital lipoid adrenal hyperplasia, resulting from steroidogenic acute regulatory protein (StAR) deficiency affecting mitochondrial cholesterol uptake, is a subtype of the disease complex with the unique characteristics of lipid accumulation leading to cell destruction." (PMID 36034654, 2022). "Mutations in STAR cause lipoid congenital adrenal hyperplasia (lipoid CAH), a disorder characterized by severe defects in adrenal and gonadal steroid production; in Leydig cells, the defects are seen mainly after the onset of hormone-dependent androgen formation." (PMID 33670702, 2021). "Perhaps, the strongest evidence for the requirement of the StAR protein in steroid biosynthesis comes from studies of lipoid congenital adrenal hyperplasia patients, where mutations in the gene encoding StAR leads to a substantial defect in the conversion of cholesterol to pregnenolone." (PMID 32756865, 2020). "Loss of StAR function causes lipoid congenital adrenal hyperplasia (LCAH)." (PMID 21647419, 2011). "Steroidogenic acute regulatory (StAR) protein deficiency is a rare autosomal recessive disorder that disrupts steroid hormone biosynthesis, resulting in congenital adrenal hyperplasia (CAH) and variations in sexual development." (PMID 41502797, 2026). "The most common cause of AI in pediatric patients is congenital adrenal hyperplasia (CAH), which is an autosomal recessive hereditary disorder caused by deficiencies in various enzymes (StAR, 3-βHSD, 17α-OH, 21-OH, and 11β-OH)." (PMID 40013223, 2025). "Congenital adrenal hyperplasia (CAH) is a group of autosomal recessive disorders caused by pathogenic variants identified in seven genes (CYP21A2, CYP11B1, CYP17A1, HSD3B2, StAR, POR, and CYP11A1) involved in the steroidogenesis pathway." (PMID 39451515, 2024). "Another example includes a StAR knockout model developed to understand congenital lipoid adrenal hyperplasia; a condition characterized by impaired steroidogenesis with typical lipid deposits in the steroidogenic tissues." (PMID 38791102, 2024). "Lipoid congenital adrenal hyperplasia (LCAH) is a rare and severe disorder that is caused by mutations in the steroidogenic acute regulatory protein (StAR)." (PMID 36407315, 2022). "Children affected by lipoid CAH have low but measurable levels of steroid hormones at birth, due to low levels of STAR-independent steroidogenesis, The demonstration of STAR-independent steroidogenesis led to the formulation of the two-hit model of lipoid CAH." (PMID 28637490, 2017). "Thus, the study of StAR and lipoid CAH continues to influence our understanding of adrenal insufficiency." (PMID 39773408, 2025). "In both patients, abdominal computed tomographic imaging showed slightly smaller adrenals with stippled calcifications, suggesting cirrhotic, end-stage fat deposition reported in nonclassical lipoid CAH due to the StAR variants." (PMID 39457196, 2024). "These do not a priori affect adrenal development, but may impact secondary organ structures as seen with steroidogenic acute regulatory protein (StAR) related lipoid CAH." (PMID 36255414, 2023). "The pathophysiology of StAR and P450scc deficiencies is similar except that lipid droplet accumulation typical of Lipoid Congenital Adrenal Hyperplasia (LCAH) caused by StAR deficiency does not occur in P450scc deficiency." (PMID 34987475, 2021). "For example, preclinical models mimicking congenital adrenal hyperplasia (CAH) phenotype provides an excellent example to investigate cell-intrinsic processes and the physiological needs of cell type-specific steroidogenesis on the varying impacts of the loss-of-function mutation in StAR." (PMID 34440620, 2021). "Furthermore, these findings match with our earlier observations showing an evident adrenal hyperplasia accompanied by an enhanced steroidogenic machinery since StAR, CYP11A1, CYP11B1, and 11β-HSD1 expression are increased in this period." (PMID 31998227, 2019).
congenital adrenal hyperplasia (continued). "For instance, although both STAR and HSD3B2 mutations can lead to congenital adrenal hyperplasia (CAH), they result in markedly different profiles of hormone production and signaling." (PMID 41357796, 2025). "Mutations in StAR result in a nonfunctional protein, which clinically translates into congenital adrenal hyperplasia and, in the case of patients with 46 XY karyotype, is accompanied by gonadal dysgenesis characterized by androgen deficiency, without alterations in anti-Müllerian hormone." (PMID 39246559, 2024). "Thus, loss of StAR function affects the first step of steroidogenesis, inhibiting all steroid production in adrenal glands and gonads, leading to the most serious form of CAH, lipoid congenital adrenal hyperplasia (LCAH, OMIM 201710)." (PMID 36733346, 2023). "Inactivating variants in STAR gene cause Lipoid Congenital Adrenal Hyperplasia (LCAH, the most severe form of CAH, OMIM#201710)." (PMID 35992119, 2022). "STAR mutations give rise to lipoid congenital adrenal hyperplasia (OMIM 201710), a severe syndrome of adrenal and gonadal insufficiency resulting in XY sex reversal; CYP11A1 defects give a similar clinical picture but without the lipid build up in steroidogenic tissues seen with STAR mutations." (PMID 29046340, 2018). "Additionally, in mammalian term placenta, no STAR activity is involved in the steroidogenesis, although mutation of this protein results in lipoid congenital adrenal hyperplasia but only after birth." (PMID 24124589, 2013). "Congenital adrenal hyperplasia (CAH) refers to a group of seven monogenic adrenal disorders, caused by pathological variants in genes coding for enzymes in the adrenal steroidogenic pathway: CYP21A2, CYP11B1, CYP17A1, HSD3B2, STAR, CYP11A1, and POR." (PMID 41450580, 2025). "Most disease-causing STAR mutations are located in the C-terminal region between exon 5 and 7, encoding for STAR related lipid transfer domain, they do not have measurable activity and cause classic lipoid CAH when homozygous or in compound heterozygosity with mutations of similar activity." (PMID 28637490, 2017). "Furthermore, mutations in the human STAR gene (STARD1) were identified in patients with congenital lipoid adrenal hyperplasia (lipoid CAH), a disorder marked by a lack of adrenal and gonadal steroidogenesis due to the inability to move cholesterol into the mitochondria [; reviewed in]." (PMID 27999527, 2016). "However, a partial loss of function of StAR has been also observed in FGD patients with normal genitalia, thus not being initially addressed as lipoid CAH (LCAH) patients." (PMID 36763264, 2023). "Therefore, the ovaries of 46,XX females with lipoid CAH do not receive the second hit until the onset of puberty, when luteinizing hormone stimulates low-levels of STAR-independent steroidogenesis." (PMID 28637490, 2017).
lipoid adrenal hyperplasia (22 papers, 2010 to 2026). "STAR mutations usually give rise to congenital lipoid adrenal hyperplasia but partial loss-of-function variants can present with an FGD-like phenotype of isolated glucocorticoid deficiency." (PMID 35418949, 2022). "Adrenal imaging was generally uninformative, showing normal sized or hypoplastic glands for most of these diagnoses, including many children with STAR mutations (congenital lipoid adrenal hyperplasia) in which enlarged adrenals are reported." (PMID 26523528, 2016). "Defects in STAR (encoding steroidogenic acute regulatory protein) disrupt the transport of cholesterol into mitochondria and classically lead to congenital lipoid adrenal hyperplasia." (PMID 26523528, 2016). "The pivotal role of StAR in the regulation of steroidogenesis was strengthened after the identification of mutations causing premature stop codons in the StAR gene of patients affected by the most common form of congenital lipoid adrenal hyperplasia (CAH), a rare disorder of steroid biosynthesis." (PMID 27065945, 2016). "In contrast to congenital lipoid adrenal hyperplasia (CLAH), which is caused by variants in the StAR, the P450scc is essential to steroidogenesis in all human tissues, including the placenta during pregnancy." (PMID 39457196, 2024). "Several “hotspots” of other forms of CAH exist (eg, 11β-hydroxylase deficiency in Jewish populations from Morocco); indeed, congenital lipoid adrenal hyperplasia due to disruption of STAR is particularly prevalent in South Korea and Japan." (PMID 34258490, 2021). "In a previous work we have isolated APOSTART, a gene containing three domains, one of which is START whose name was given after the discovery of the StAR gene that is involved in human congenital lipoid adrenal hyperplasia." (PMID 32824095, 2020). "In non-classic congenital lipoid adrenal hyperplasia, due to partial loss-of-function of STAR, the picture is mixed with both normal sized and hypoplastic adrenals described." (PMID 35418949, 2022). "The StAR gene maps to the gene locus 8p11.2 and has been identified only recently as causing non-classic lipoid adrenal hyperplasia in a first series of patients in 5 families." (PMID 21647419, 2011).
endometriosis (15 papers, 2015 to 2025). The growth of functional endometrial tissue in anatomic sites outside the uterine body. "High expression of StAR in FBs played an important role in the development of endometriosis, and its effect was assessed in this study." (PMID 34233737, 2021). "We also identified fibroblast subpopulations related to endometriosis development and found that StAR played an important role in this process." (PMID 34233737, 2021). "StAR was essential for catalytic conversion of cholesterol to E2, which was necessary for endometriosis development." (PMID 34233737, 2021). "It has been shown that a decreased level of miR-23a and b in endometrium of women with endometriosis releases an elevated expression level of SF-1, as well as of the steroidogenic acute regulatory protein (StAR) and of CYP19." (PMID 33153202, 2020). "Additionally, they are involved in steroid hormone metabolism via the Steroidogenic Acute Regulatory Protein (STAR) gene, whose expression is closely associated with endometriosis." (PMID 39796089, 2024). "In endometriosis, estradiol is made available through systemic hormones and locally in the peritoneal environment through aromatase and steroidogenic acute regulatory protein (StAR) activity." (PMID 34073257, 2021). "We also found that aromatase (CYP19A1) and steroidogenic acute regulatory protein (StAR), were highly expressed in endometriosis FBs, which could increase oestrogen levels and expression of StAR both of which contribute to the development of the disease." (PMID 34233737, 2021). "Immunofluorescence confirmed that C3, C7, StAR and S100A10 were expressed more abundantly in endometriosis FBs." (PMID 34233737, 2021). "A few studies reported detectable levels of the enzymes involved in the generation of DHEA from cholesterol (StAR, CYP11A1 and CYP17A1) in endometriosis, suggesting that, in contrast to eutopic endometrium, endometriosis is able to produce steroids from cholesterol." (PMID 30283331, 2018). "Such increased SF-1 expression or activity in endometriotic tissue could result in increased activity of steroid acute regulatory protein (StAR) and aromatase (CYP19A1), resulting in increased local estrogen biosynthesis, a key pathological feature of endometriosis." (PMID 32370117, 2020).